NAT14 (N-acetyltransferase 14 (putative))
Description:
Probable acetyltransferase. May act as a transcription factor that regulates the expression of coproporphyrinogen oxidase by binding to a promoter regulatory element.
Synonyms: KLP1
Tractability: Antibody: UniProt predicts a signal peptide or a membrane-spanning region. PROTAC: its protein half-life has been measured.
Gene: Protein-coding gene on chromosome 19 (55,485,188 to 55,487,569, forward strand). Ensembl gene ENSG00000090971.
Subcellular location: Membrane
Subcellular location (Human Protein Atlas): Mitochondria
Gene Ontology:
Molecular function: protein binding; N-acetyltransferase activity; acyltransferase activity, transferring groups other than amino-acyl groups
Biological process: DNA-templated transcription initiation; positive regulation of DNA-templated transcription
Cellular component: nucleus; membrane
Genetic constraint (gnomAD): Loss-of-function variants: 14 observed, 6.94 expected, observed/expected ratio (o/e) 2.02. That is too few expected variants to judge how well the gene tolerates losing a copy. Missense variants: 341 observed, 214.5 expected, observed/expected ratio (o/e) 1.59, 90% interval 1.45 to 1.74. Synonymous variants: 156 observed, 102.7 expected, observed/expected ratio (o/e) 1.52, 90% interval 1.33 to 1.74.
Homologues: Orthologues: chimpanzee NAT14 (99% identical), macaque NAT14 (99% identical), guinea pig NAT14 (96% identical), pig NAT14 (96% identical), dog NAT14 (96% identical), mouse Nat14 (95% identical), tropical clawed frog nat14 (48% identical), zebrafish nat14 (37% identical). Paralogues in human: ASPNAT (20% identical), NAT8 (18% identical).
Diseases named in the same sentence as NAT14 in open-access papers:
NAT14 is named in the same sentence as 4 diseases in open-access papers, as found by Europe PMC text mining. Sharing a sentence is not in itself a finding about the gene and the disease. The quoted sentences say what the papers report.
cervical cancer (1 paper, 2023). A primary or metastatic malignant neoplasm involving the cervix. "In particular, seven genes showed higher expression in cervical cancer and positively correlated with EMT scores, including CSRP2BP, LPCAT1, NAT14, CREBBP, MSL3, ATF2 and GNPNAT1." (PMID 37845756, 2023).
NAT14 also shares sentences with these, for which no sentence is quoted: breast carcinoma (1 paper); congenital hydrocephalus (1); tumor (1).